ACBD3 (acyl-CoA binding domain containing 3)
Description:
Involved in the maintenance of Golgi structure by interacting with giantin, affecting protein transport between the endoplasmic reticulum and Golgi. Involved in hormone-induced steroid biosynthesis in testicular Leydig cells (By similarity). Recruits PI4KB to the Golgi apparatus membrane; enhances the enzyme activity of PI4KB activity via its membrane recruitment thereby increasing the local concentration of the substrate in the vicinity of the kinase. (Microbial infection) Plays an essential role in Aichi virus RNA replication by recruiting PI4KB at the viral replication sites.
Synonyms: GOCAP1; GOLPH1; GCP60; PAP7
Tractability: Antibody: UniProt places it where antibodies can reach, with high confidence. PROTAC: ubiquitination databases record sites on it; its protein half-life has been measured.
Gene: Protein-coding gene on chromosome 1 (226,144,679 to 226,186,762, reverse strand). Ensembl gene ENSG00000182827.
Subcellular location: Golgi apparatus membrane; Mitochondrion
Subcellular location (Human Protein Atlas): Golgi apparatus
Pathways (Reactome):
Vesicle-mediated transport: Golgi Associated Vesicle Biogenesis
Gene Ontology:
Molecular function: protein binding; protein kinase A regulatory subunit binding; protein-membrane adaptor activity; fatty-acyl-CoA binding
Biological process: endoplasmic reticulum to Golgi vesicle-mediated transport; Golgi organization
Cellular component: Golgi apparatus; Golgi membrane; membrane; mitochondrion
Genetic constraint (gnomAD): Loss-of-function variants: 29 observed, 62.42 expected, observed/expected ratio (o/e) 0.46, 90% interval 0.34 to 0.63. The upper end of that interval is the gene's LOEUF score, 0.63, which puts it in group 2 of 6, group 1 being the genes least tolerant of losing a copy. Missense variants: 540 observed, 615.82 expected, observed/expected ratio (o/e) 0.88, 90% interval 0.82 to 0.94. Synonymous variants: 278 observed, 241.3 expected, observed/expected ratio (o/e) 1.15, 90% interval 1.04 to 1.27.
Homologues: Orthologues: chimpanzee ACBD3 (99% identical), macaque ACBD3 (99% identical), dog ACBD3 (96% identical), rabbit ACBD3 (96% identical), pig ACBD3 (96% identical), guinea pig ACBD3 (93% identical), mouse Acbd3 (89% identical), tropical clawed frog acbd3 (79% identical), zebrafish acbd3 (73% identical), zebrafish ACBD3 (53% identical), Caenorhabditis elegans Y41E3.7 (38% identical), Drosophila melanogaster CG14232 (37% identical). Paralogues in human: TMED8 (21% identical).
Diseases named in the same sentence as ACBD3 in open-access papers:
ACBD3 is named in the same sentence as 42 diseases in open-access papers, as found by Europe PMC text mining. Sharing a sentence is not in itself a finding about the gene and the disease. The quoted sentences say what the papers report.
breast carcinoma (7 papers, 2019 to 2024). "In this context, it is worth noting that ACBD3, Arf1, PI4Kβ and Rab4A all have been implicated in breast cancer progression and prognosis and found to be coordinately regulated in the same region of chromosome 1q." (PMID 37048152, 2023). "Several transcription regulators and regulatory pathways were associated with increased ACBD3 expression in breast tissue, and some of these were linked to breast cancer." (PMID 36012147, 2022). "High ACBD3 expression was associated with poorer distant metastasis-free survival in ER+ breast cancer patients." (PMID 36012147, 2022). "High ACBD3 expression in breast cancer samples was associated with PR negativity and HER2 negativity." (PMID 36012147, 2022). "In breast cancer, ACBD3 mutations occurred in 5 out of 1084 patients; these included E212Q, E226K, E348Q, and R523T mutation, as well as a E348Nfs*21 frame shift deletion." (PMID 36012147, 2022). "Bioinformatic databases were queried to characterise ACBD3 expression and mutation in breast cancer and to investigate how overexpression affects breast cancer patient outcomes." (PMID 36012147, 2022). "Lastly, but importantly, it has been reported that ACBD3 is up-regulated in breast cancer and associated with advanced pathoclinical features as well as poor prognosis in breast cancer." (PMID 31022988, 2019). "ACBD3 has many interactors, some of which are implicated in breast cancer in their own right." (PMID 36012147, 2022). "Existing studies have shown that ACBD3 mediates the malignant process of breast cancer by regulating the intracellular β-84 catenin signaling pathway." (PMID 38098097, 2023). "Contrary to previous reports, ACBD3 protein staining results for this array found ACBD3 protein staining to be statistically lower in malignant breast cancer tissue compared to adjacent tissue or normal adjacent tissue." (PMID 36012147, 2022). "There was significantly less survival, more relapse, and more distant metastasis in ER+ patients when divided by ACBD3 expression, and ACBD3 overexpression appears to be universally detrimental to breast cancer prognosis." (PMID 36012147, 2022). "ACBD3 protein levels were significantly higher in PR− breast cancers (mean = 3.296) compared to breast cancers with high expression of PR (PR 3+) (mean = 2.642) (* p = 0.022)." (PMID 36012147, 2022). "Little is known about the regulation of ACBD3, despite the number of important cellular pathways it participates in, and there is a wide scope for a breast cancer role beyond CSC formation by Wnt signaling." (PMID 36012147, 2022). "This study has found further evidence implicating ACBD3 in the Wnt signaling pathway and an additional ACBD3 association with CSC-maintaining proteins in breast cancer." (PMID 36012147, 2022). "Breast cancers were found to have the highest proportion of ACBD3 gene amplifications, at 8.76%, relative to other cancers such as uterine and prostate, and mutation frequency was low across all the cancers examined." (PMID 36012147, 2022). "The findings here also support the current evidence for ACBD3 involvement in breast cancer stem cells." (PMID 36012147, 2022). "Relationships between ACBD3 and all three major breast cancer hormone and signaling receptor pathways (ER, HER2, and PR) have been found." (PMID 36012147, 2022). "The probability of overall survival (OS) was reduced in breast cancer patients with tumor ACBD3 expression above the median level." (PMID 36012147, 2022). "KDM2B inhibits senescence and, like ACBD3, is implicated in CSC self-renewal and Wnt/β-Catenin signaling in breast cancer." (PMID 36012147, 2022). "HER2− breast cancer samples had significantly higher ACBD3 protein expression than HER2 1+ breast cancer samples (2.038, n = 49, versus 1.055, n = 4, respective mean averages, p = 0.0107)." (PMID 36012147, 2022). "ACBD3 protein level expression in breast cancer is currently limited to 11 samples in the GEPIA database and a dataset from a single publication." (PMID 36012147, 2022).
breast carcinoma (continued). "Breast cancer ACBD3 expression had a larger interquartile range, smaller minimum value, higher maximum value, and more numerous and distant outliers beyond the maximum range and were significantly higher than in matched healthy tissue." (PMID 36012147, 2022). "Breast cancer had one of the highest levels of ACBD3 protein expression by the methodology used (11 out of 11 patient samples had medium levels of ACBD3 staining)." (PMID 36012147, 2022). "High ACBD3 expression was found to be detrimental to breast cancer patient outcomes across many subgroups, and there were also small changes in response to certain therapies depending on ACBD3 expression." (PMID 36012147, 2022). "Increased ACBD3 expression has previously been found to correlate with poor breast cancer patient prognosis and is overexpressed in commercial breast cancer cell lines." (PMID 36012147, 2022). "A large number of factors were discovered that bind within 10,000 bases of the ACBD3 transcription start site across all tissues, and some of these stand out as having roles in breast cancers, including NOTCH1-NICD, CDK9, CTCF, and CEBPB." (PMID 36012147, 2022). "It was shown that up-regulating ACBD3 promoted the self-renewal and tumorigenesis of breast cancer cells via activating the Wnt/beta-catenin signaling pathway." (PMID 31022988, 2019). "The expression of ACBD3 ranked high in breast cancer, kidney cancer, and myeloma tumor cell lines." (PMID 38098097, 2023). "Finally, ACBD3 expression in normal, adjacent, and cancerous tissue was assessed to examine possible relationships between breast cancer subtypes and patient characteristics." (PMID 36012147, 2022). "We showed that ACBD3 expression was almost doubled in breast cancer compared to healthy tissue but that changes in expression were not related to increased copy number or changes in methylation patterns, suggesting that other mechanisms were responsible for ACBD3 over-expression." (PMID 36012147, 2022). "ACBD3 reduces NOTCH signaling in conjunction with NUMB, but NUMB and NUMB-L are downregulated in breast cancers and NUMB-deficient breast cancer cells form increased cancer stem cell (CSC) pools, suggesting that ACBD3 may promote CSCs independently of NUMB." (PMID 36012147, 2022). "This study further investigated ACBD3′s role in breast cancer." (PMID 36012147, 2022). "There is some precedent for this, as ACBD3 was found to be suppressed by ER signaling but is highest in ER+ cell lines, suggesting that repressors of ACBD3 may be reprogrammed in breast cancer." (PMID 36012147, 2022). "ACBD3 appears to be a candidate biomarker for poor patient prognosis in breast cancer and may possibly be a biomarker for ER signal reprogramming or of precancerous breast tissue." (PMID 36012147, 2022). "Given that ACBD3 has previously been reported to be upregulated in breast cancer and that our bioinformatic data supported this, coupled with our survival analyses supporting previous findings, we do not believe that genetic heterogeneity of different cohorts can explain these differences." (PMID 36012147, 2022). "Interaction with one of the major breast cancer hormone receptor pathways could explain these results, indicating that there is a real need for study into the ACBD3-(ER, PR, HER2) relationships." (PMID 36012147, 2022). "In addition, databases were queried to investigate the link between ACBD3 expression and survival, relapse and metastatic outcomes for patients divided by receptor status, breast cancer subtype, and response to chemotherapeutic agents." (PMID 36012147, 2022). "The aim of this study was to determine whether ACBD3 is overexpressed in breast cancer, to investigate whether its expression impacts patient survival, and to consider the broader implications of breast cancer ACBD3 expression in terms of its interactions." (PMID 36012147, 2022). "ACBD3 is located on chromosome 1 arm q, which is frequently amplified in breast cancers." (PMID 36012147, 2022).
breast carcinoma (continued). "IHC analysis found that ACBD3 levels varied based on hormone receptor status, indicating that ACBD3 could be a candidate biomarker for poor patient prognosis in breast cancer and may possibly be a biomarker for ER signal reprogramming of precancerous breast tissue." (PMID 36012147, 2022). "ACBD3 overexpression has previously been found to correlate with worse prognosis for breast cancer patients and, as an incredibly diverse protein in both function and cellular localisation, ACBD3 may have a larger role in breast cancer than previously thought." (PMID 36012147, 2022). "This could explain why breast cancer patient relapse is more likely when ACBD3 expression is high." (PMID 36012147, 2022). "The KMplotter breast cancer mRNA gene chip database was used to look at differences in survival, relapse, and distant metastasis in breast cancer patients based on whether mRNA levels of ACBD3 were above or below the median expression level in their breast tumor." (PMID 36012147, 2022). "The location of ACBD3 on chromosome 1q and recent findings of a CSC promoting role in breast cancer make ACBD3 a candidate for further study in breast cancer research." (PMID 36012147, 2022). "The amplification rate of ACBD3 in breast cancer was less than expected based on the ACBD3 transcriptional upregulation observed with the GEPIA tool and the commonality of chromosome 1q amplification in breast cancer." (PMID 36012147, 2022). "ACBD3, from the same family as ACBD7, has been found to be up-regulated in a variety of tumor tissues and may be responsible for poor breast cancer prognosis." (PMID 38329437, 2024). "IHC staining of ACBD3 in breast cancer patient core samples did not support previously published data." (PMID 36012147, 2022). "HER2+ breast cancer patients who had complete pathological response to chemotherapy had lower ACBD3 RNA expression than those who did not respond." (PMID 36012147, 2022). "ACBD3 may even be the target of downregulation in response to breast cancer that cancerous cells do not respond to but that normal cells surrounding them do." (PMID 36012147, 2022). "Biomax arrays with over 300 tissues cores were chosen to compare cancerous tissue with normal adjacent tissue, in addition to a comparison of expression between different breast cancer subgroups, with an emphasis on ACBD3 expression in receptor-positive versus receptor-negative breast cancers." (PMID 36012147, 2022).
lung carcinoma (5 papers, 2015 to 2025). "Conversely, overexpression of ACBD3 in 1q-diploid murine lung cancer 393 P cells increased subcutaneous tumor size." (PMID 40189704, 2025). "Conversely, overexpression of ACBD3 in mesenchymal lung cancer cells reduced NOTCH activity, and deletion of the NUMB binding domain abolish this effect." (PMID 40189704, 2025). "In a panel of human lung cancer cell lines, both ACBD3 mRNA and protein levels are downregulated in mesenchymal-like cells." (PMID 40189704, 2025). "Consistent with its role in promoting tumor growth, ACBD3 expression levels are higher in human lung cancers compared to normal tissues." (PMID 40189704, 2025). "Knockdown of SNAI1 mitigated ACBD3 deficiency-induced cell migration and invasion and anoikis resistance in epithelial H441 cells, suggesting that ACBD3 suppresses lung cancer cell dissemination through inhibiting the NOTCH-SNAI1 axis." (PMID 40189704, 2025). "In this study, we demonstrated that ACBD3 promotes the growth of primary lung tumors with 1q amplifications but acts as a suppressor of metastasis in 1q-diploid lung cancer cells." (PMID 40189704, 2025). "Conversely, in chromosome 1q-diploid lung cancer cells, ACBD3 acts as a suppressor of lung cancer metastasis by inhibiting the NOTCH signaling pathway and reducing cancer cell motility." (PMID 40189704, 2025). "Interestingly, ACBD3 depletion impaired the proliferation of 1q-LUAD cells while exhibiting minimal effect on the growth of 1q-diploid lung cancer cells." (PMID 40189704, 2025). "Depletion of ACBD3 in epithelial human lung cancer cells increased NOTCH reporter activity." (PMID 40189704, 2025). "However, the role of ACBD3 in the Golgi secretory pathway and in lung cancer progression remains poorly understood." (PMID 40189704, 2025). "Next, we investigated the role of ACBD3 in lung cancer metastasis." (PMID 40189704, 2025). "To determine which proteins are responsible for recruiting PI4KB in lung cancer cells, we conducted a biotin proximity labeling assay using TurboID-fused PI4KB or PI4K2A as the baits, revealing ACBD3 and ARMH3 as major PI4KB binding partners." (PMID 40189704, 2025). "In addition, ACBD3 may be involved in the progress of gefitinib on lung cancer cells." (PMID 38098097, 2023). "In this context, ACBD3 has minimal or moderate impact on cell proliferation but acts as a negative regulator of NOTCH signaling, resulting in reduced SNAI1 expression and impaired cell motility in mesenchymal lung cancer cells." (PMID 40189704, 2025). "For instance, lung cancer patients with 1q-amplified LUAD, which express high levels of ACBD3, may benefit from therapies targeting ACBD3." (PMID 40189704, 2025). "This aligns with a previous research showing that ACBD3 is among the most downregulated genes in small cell lung cancer, a highly metastatic lung cancer subtype, compared to NSCLC, implying that ACBD3 may act as a negative regulator of lung cancer metastasis." (PMID 40189704, 2025).
viral infection (5 papers, 2017 to 2025). "In this review, we discuss the mechanisms underlying the involvement of ACBD3 in viral infection at MCSs." (PMID 32322249, 2020). "Although ACBD3 KO had multiple effects on viral infection, it also reduced the number of infected cells quantified by fluorescence microscopy." (PMID 40207930, 2025). "With the accumulating investigations of the role of ACBD3 in viruses, the mechanisms by which ACBD3 is involved in viral infection are gradually being elucidated." (PMID 32322249, 2020). "In immunoprecipitation assay, the 3A proteins from these strains were immunoprecipiated by anti-ACBD3 antibody after virus infection." (PMID 28303920, 2017). "In most cases, ACBD3 plays a positive role in viral infection." (PMID 32322249, 2020). "The aim of this mini-review is to summarize the role of ACBD3 at MCSs during viral infection." (PMID 32322249, 2020). "On the other hand, some viral proteins have been shown to interact with ACBD3 to drive the formation of large complexes, such as viral protein/ACBD3/PI4KB (phosphatidylinositol-4-kinase B), following viral infection." (PMID 39723831, 2025). "In addition, neither virus infection nor the expression of enterovirus 3A proteins alone elicited PI4KB recruitment in the absence of ACBD3." (PMID 30755512, 2019).
steatosis (4 papers, 2015 to 2025). Increased lipid within the cytoplasm of cells. "In pathological conditions, the PPARα level increases, determining the activation of acyl-CoA-binding domain-containing 3 (ACBD3), CPT2, and of fatty acid transport protein SLC27A, and ultimately reducing steatosis." (PMID 41226441, 2025). "When the level of PPARα is increased, its target gene carnitine palmitoyltransferase 2 (CPT2) and the acyl-CoA binding domain containing 3 (ACBD3) or the solute carrier family 27A (SLC27A) are activated, and the steatosis is reduced." (PMID 30931332, 2019). "PPARα restoration led to the transcriptional activation of genes associated with lipid metabolism, including carnitine palmitoyltransferase 2 (CPT2) and acyl-CoA binding domain containing 3 (ACBD3), and then resulted in the steatosis resolution." (PMID 29018509, 2017). "Interestingly, the expression of liver fatty acid transport-related genes, including SLC27A4, ACBD3 and SLC27A1, were significantly reduced in FFA induced steatosis cells or HFD induced steatotic liver compared with control groups." (PMID 26330104, 2015).
Huntington disease (3 papers, 2015 to 2024). Huntington disease (HD) is a rare neurodegenerative disorder of the central nervous system characterized by unwanted choreatic movements, behavioral and psychiatric disturbances and dementia. "GCP60 (also called acyl–CoA binding domain containing 3, or ACBD3) levels have also been shown to be elevated in Huntington’s disease due to an expanded polyglutamine repeat sequence in huntingtin." (PMID 38525704, 2024). "ACBD3 (also known as GCP60) is upregulated in cell culture models expressing the huntingtin (Htt) protein with expanded polyglutamine repeats, as well as in the brains of mice that model Huntington disease and in the striatum of Huntington's patients." (PMID 26594142, 2015).
adrenocortical carcinoma (2 papers, 2022 to 2023). "The survival of four tumors was correlated with the expression level of ACBD3, including pancreatic adenocarcinoma, adrenocortical carcinoma, sarcoma, and glioma." (PMID 38098097, 2023). "Three other tumor types, adrenocortical carcinoma, kidney chromophobe, and uterine corpus endometrial carcinoma, showed downregulation of ACBD3 mRNA expression compared to matched normal tissue." (PMID 36012147, 2022).